GSDMD (gasdermin D)
Diseases named in the same sentence as GSDMD in open-access papers (continued):
Sharing a sentence is not in itself a finding about the gene and the disease.
infection (continued). "While ΔespL infection triggered comparable MLKL phosphorylation between WT, Tnfr1−/− and TrifLps2 macrophages, caspase-1 processing, GSDMD cleavage and macrophage lysis were reduced in TrifLps2 macrophages compared to WT and Tnfr1−/− macrophages." (PMID 40128366, 2025). "We also show that despite this temporal difference in activation, suppression of both GSDMD and GSDME is required to significantly dampen both cell lysis and inflammation following Brazil/78 infection, suggesting possible redundancy." (PMID 40481027, 2025). "Our findings showed that GSDMD cleavage occurs after stimulation with LPS + Ng, whereas GSDME is cleaved after infection with VSV in human and mouse cells." (PMID 41550948, 2025). "Compared to mock controls, H6N6 infection significantly upregulated NLRP3, caspase-1, and GSDMD mRNA at 12, and 24 hpi (p < 0.05)." (PMID 41305513, 2025). "Suppression of GSDMD and/or GSDME expression was confirmed at 24 h following infection via immunoblot." (PMID 40481027, 2025). "Gasdermin D (GSDMD) is the executor of pyroptosis, which is important for host defense against pathogen infection." (PMID 39439418, 2024). "Since NLRP3-dependent pyroptosis is executed by GSDMD, we also depleted GSDMD to verify its role in RVFV-infection induced IL-1β release." (PMID 39213434, 2024). "At 4h post-infection, LV-NLRP12 cells showed elevated CASP1 and GSDMD cleavage, followed by higher levels of active IL−1β and IL-18." (PMID 39119293, 2024). "In the infection group, the relative mRNA expression of NLRP3 and GSDMD was significantly raised compared to the control group (p < 0.01)." (PMID 38515339, 2024). "Our findings demonstrated that recognition of MDR A. baumannii 1605 infection by the host activates the caspase-1 and caspase-11, resulting in NLRP3/ASC inflammasome activation and the formation of GSDMD pores and induction of programmed cell death." (PMID 39533032, 2024). "During IAV-infection ZBP1 can also engage pyroptosis by caspase-1 activation and gasdermin D (GSDMD) pore formation." (PMID 38778049, 2024). "In the current study, we characterized the relative contributions of T3SS, the NLRP3 versus the NLRC4 inflammasomes, and GSDMD and GSDME to IL-1β release and pyroptosis in neutrophils versus macrophages following infection with P. aeruginosa." (PMID 37730693, 2023). "In WT macrophages, we observed PI incorporation after 4 h infection and this early cell permeabilization was GSDMD and Caspase-1/11-dependent and NLRP3 independent, suggesting that GSDMD cleavage occurs upstream to the NLRP3 inflammasome activation." (PMID 36828815, 2023). "The whole process was driven by infection of mice with Clostridium difficile (C. difficile) to induce NLRP3 inflammasome leading to pyroptosis and IL-1β release through pore forming GSDMD." (PMID 38087059, 2023). "At 31 h post-infection, when the ZIKV-infected cells were permissive to PI staining, secreted GSDMD was also detected in the culture supernatant." (PMID 36699618, 2023). "At the same time, Nlrp3, Caspase-1, and GSDMD-N significantly increased after infection with PEDV, while GSDMD significantly decreased." (PMID 38132483, 2023). "Lastly, in vitro infection of normal human bronchial epithelial (HBEC-3KT) cells with human H1N1 and H3N2 IAV resulted in GSDMD cleavage, with active p30 and inactive p43 subunits of GSDMD detected in cell supernatants at 24 h following infection." (PMID 37945599, 2023). "We found that after 2 h infection, Leishmania induces ASC oligomerization, and this process was GSDMD-dependent." (PMID 36828815, 2023). "Immunoblot analysis detected GSDMD-NT, known as pyroptosis executor, in the RAW264.7 cells at 12 hours post infection." (PMID 37009510, 2023). "At the same early time of 12 h post-infection, the RIPK3 KO BMDMs started to diverge from the ZBP1 KO cells and began to show the activation of caspases and GSDMD and GSDME." (PMID 38005819, 2023).
infection (continued). "Using immunoblotting-based biochemical analyses, we observed IAV-induced PANoptosis in BMDMs at both 12 and 24 h post-infection, as indicated by activation of CASP1, gasdermin D (GSDMD) and GSDME, along with CASP8, CASP3, and CASP7, as well as MLKL." (PMID 38005819, 2023). "Research has shown that after infection with SVV markedly increases pig GSDMD cleavage and cell pyroptosis, confirming the inducible effect of SVV 3Cpro on GSDMD cleavage and pyroptosis." (PMID 37869659, 2023). "On the other hand, caspase-1 activation can also cleavage and activate gasdermin D (GSDMD), the final effector of pyroptosis, a strong inflammatory process that leads to cell death in response to infection." (PMID 35628443, 2022). "However, GSDMD deficiency did not prevent the death of HeLa cells induced by 1906I infection." (PMID 35186798, 2022). "To examine global transcriptional effects of CASP11 and GSDMD in the lung during SARS–CoV-2 infections, we infected WT, Casp11−/−, and Gsdmd−/− mice and performed RNA sequencing on lung RNA at 2 d after infection." (PMID 35588457, 2022). "For example, it has been reported that the Shigella ubiquitin ligase IpaH7.8 mediates the ubiquitylation of N-terminal PFD in human GSDMD and GSDMB and promotes their degradation in immune cells to prevent pyroptosis, enabling infection." (PMID 36093182, 2022). "Western blotting analyses uncovered that the cleavages of IL-1β (p17) and GSDMD (N-GSDMD) in the supernatants, and the production of pro-IL-1β in the cell lysates were induced by ECHO 11 infection." (PMID 36026486, 2022). "Compared with that in the control, the number of TUNEL-positive cardiomyocytes in GSDMD-KO mice treated with DOX was reduced; however, this effect was reversed by AAV9-GSDMD-OE infection." (PMID 36289195, 2022). "After 48 h post-infection, the mRNA expressions of NLRP3 and GSDMD were higher in the RHwx2−/− group compared with the RH and RHwx2+/+ groups, and the difference was statistically significant (P < 0.05)." (PMID 36471417, 2022). "The GSDMD−/− mice were treated i.p. with MAB453 or IgG 1 h prior to infection and 23 h post-infection." (PMID 34011393, 2021). "During human adenoviruses (HAdV) infection, AIM2 inflammasome can activate caspase-1 and facilitate GSDMD cleavage in monocyte-derived DCs, resulting in pyroptosis." (PMID 34899666, 2021). "The GSDMD−/− mice were treated i.p. with SB225002 (Cxcr2 inhibitor) or vehicle 1 h prior to infection and 23 h post-infection." (PMID 34011393, 2021). "The IOD value of PI staining and the expression of GSDMD mRNA were significantly increased, with higher values in the HPI+ infection group than that in the HPI−." (PMID 33678162, 2021). "HPI+/HPI−-infection was accompanied by upregulated expression levels of NLRP3, ASC, caspase-1, IL-1β, IL-18 and GSDMD, with significantly higher levels detected in the HPI+ group compared to those in the HPI− group (P < 0.01 or P < 0.05)." (PMID 33678162, 2021). "To validate that NLRP6 induces pyroptosis, we assessed the expression of caspase-1 and gasdermin-D in BMDMs from WT and NLRP6 KO mice after infection with S. aureus (MOI of 20) for 8 hours." (PMID 30248149, 2018). "Interestingly, these authors demonstrated that GSDMD-dependent neutrophil death impairs the control of extracellular bacteria E. coli, thus suggesting that GSDMD could exert an anti-inflammatory role depending on the infection context." (PMID 30459758, 2018). "Taking together, the results demonstrate that PToV 3CLP, driven by rVSV infection, induces a potent and specific GSDMD-mediated pyroptosis that is independent of the VSV-triggered and GSDME-mediated cell pyroptosis in IPEC-J2 cells." (PMID 41400836, 2026). "We observed substantial levels of GSDMD-dependent cell death in mT3Sf-infected CASP4–/– cells (mediated by NLRC4) and in NLRC4–/– cells (mediated by CASP4), confirming that mT3Sf::empty infection induces pyroptosis via activation of both of these two main cell death pathways." (PMID 41533441, 2026).
infection (continued). "Infection with mT3Sf::empty induced cell death of infected THP-1 human macrophages, and this death was reduced in CASP4/NLRC4–/– double knockout cells to the background levels seen in control GSDMD–/– cells." (PMID 41533441, 2026). "Further analysis revealed a slight increase in p-MLKL and the presence of mildly cleaved Gasdermin D (GSDMD) at a high MOI (multiplicity of infection), although these changes were not significant, and no cleaved form of Gasdermin E (GSDME) was observed." (PMID 40891826, 2025). "During human rhinovirus (hRV) infection, inflammasome-mediated IL-1β secretion and pyroptosis in nasal epithelial progenitor cells and nasal epithelial cells depend on the DDX33/ DDX58- NLRP3- caspase-1- GSDMD axis." (PMID 39994107, 2025). "However, in Aim2–/– pBMDMs, there was a complete absence of activation of pyroptotic molecules, including CASP1 and gasdermin D (GSDMD), upon MPXV infection." (PMID 41225161, 2025). "Protein-level validation showed that the activation of key cell death markers, including Caspase-3, GSDMD, and MLKL, significantly increased as the infection progressed, with their dynamic changes correlating strongly with the expression pattern of viral proteins." (PMID 40076601, 2025). "GFP-tagged GSDMD was expressed in RIPK3 expressing HeLa (HeLa-RIPK3) cells, in which we previously reported that co-treatment of TNF and TAK1 inhibitor mimics pathogen infection and induces mitochondrial ROS." (PMID 40533460, 2025). "Notably, inflammasome scores (based on IL1B, IL18, NLRP3, GSDMD, PYCARD) remained stable in YG CMs and IMs during infection but increased consistently in AG subsets from 4 to 6 dpi." (PMID 40794649, 2025). "However, dual silencing of GSDMD and GSDME was required to reduce IL-1β secretion following Brazil/78 infection." (PMID 40481027, 2025). "IL-1β and IL-18 levels were reduced in the lungs of Gsdmd−/− mice after infection but levels of these cytokines were not entirely dependent on GSDMD, despite the canonical role of GSDMD in IL-1β and IL-18 release." (PMID 38553499, 2024). "p. i, but it induced lower levels of IL-1β, IL-18, and GSDMD-NT, which led to an alleviated inflammatory infiltration and pathological damage in the lungs and brains, and a lower death rate compared with wild-type PRV strain infection." (PMID 39316625, 2024). "Indeed, these results are in accord with our published findings that IL-1β levels in the lung at day 2 post infection with SARS-CoV-2 are dependent on GSDMD, but that IL-1β release occurs in a GSDMD-independent manner at later timepoints post infection." (PMID 38553499, 2024). "Infection with both L. mexicana strains resulted in similar GSDMD cleavage showing that the phenotype observed did not arise during in vitro culture of the parasites." (PMID 39250503, 2024). "The decreases in inflammation in the absence of GSDMD do not affect virus loads or hinder recovery from infection." (PMID 38553499, 2024). "We also observed increased levels of cleaved PARP1 in WT and GSDMD KD cells after infection indicating that cell death induced by infection was not broadly prevented by GSDMD depletion, though lactate dehydrogenase release was decreased in GSDMD KD cells." (PMID 38553499, 2024). "In the innate immune system, AMs serve as the earliest replicative ecological niche for Mtb, and upon infection by Mtb, ESAT-6 secretion system 1 (ESX-1) induces inflammasome activation and, subsequently, the formation of caspase-1 can cleave gasdermin-D (GSDMD) pores and the release of IL-1β." (PMID 39456188, 2024). "As in other myeloid cell types, LPS transfection or infection with the Gram-negative bacterial pathogen Citrobacter rodentium induces caspase-11 activation, GSDMD cleavage and IL-1β secretion in human and murine neutrophils." (PMID 37939552, 2023). "By contrast, at 24 h infection, only the non-infected cells contain active GSDMD, suggesting that Leishmania inhibits the canonical cleavage of GSDMD latter after infection." (PMID 36828815, 2023).
infection (continued). "We found that endogenous GSDMD is cleaved in response to Leishmania amazonensis after 2 h infection but not after 24 h." (PMID 36828815, 2023). "We also examined the role of GSDMD and GSDME during infection." (PMID 37730693, 2023). "Consistent with our recent findings, IAV infection reduced AM numbers in the airways of wildtype mice on day 3 and 5 post-infection and a similar reduction was observed in the absence of GSDMD." (PMID 37945599, 2023). "This demonstrates that lack of GSDMD exclusively in BM-derived cells is sufficient to observe higher lamina propria S.Tm loads after 72 h of infection." (PMID 37988464, 2023). "In this study, the absence of GSDMD limited the production of several key pro-inflammatory mediators in the airways, which correlated with increased resistance to infection, namely improved survival, as well as reduced lung viral burden and pathology." (PMID 37945599, 2023). "Overall, these observations clearly demonstrate using genetic and pharmacological approaches that neither GSDMD nor GSDME are required for NETosis induced by PMA or following infection with T3SS expressing P. aeruginosa." (PMID 37730693, 2023). "We did not observe any differences in the kinetics of Salmonella-induced cell death in ex vivo BMDM infection assays, nor inflammasome activation, measured by GSDMD cleavage." (PMID 37770424, 2023). "IpaH7.8 does not bind mouse GSDMD, in which the α1–β1’ motif is not conserved, leading to the inability of Shigella to efficiently establish infection in the mouse." (PMID 36991122, 2023). "Remarkably, oxidized phospholipids induce a CASP4/11-dependent cytokine response without inducing GSDMD-dependent cell death, thus mirroring our in vivo results in which Casp11−/− mice fare better during infection while Gsdmd−/− mice do not." (PMID 35588457, 2022). "Our data showed that ECHO 11 infection or LPS/Nigericin treatment induced pro-IL-1β maturation, and CASP-1/GSDMD cleavages in THP-1 cells, and these activations were remarkably attenuated by knocking down either one of the NLRP3 inflammasome components and pyroptosis." (PMID 36026486, 2022). "Furthermore, ECHO 11 infection triggered NLRP3 inflammasome activation, as evidenced by cleavages of GSDMD, pro-IL-1β and pro-caspase-1, and the release of LDH." (PMID 36026486, 2022). "Spleen from GSDMD+/+ and GSDMD-/- mice showed clear signs of damaged white pulp structure after SEZ infection, but more hemosiderin could be observed in the spleen of GSDMD-/- mice than in the spleen of GSDMD+/+ mice after the infection." (PMID 36311722, 2022). "Compared to GSDMD-deficient mice, deletion of NLRC4 alone showed an increase in tissue damage and weight loss during infection but no significant increase in the bacterial burden." (PMID 35801644, 2022). "We next determined whether the pyroptosis executors, GSDMD and GSDME, were activated during the infection of JEG-3 cells with ZIKV." (PMID 35972780, 2022). "Caspase-1−/− and Asc−/− BMDMs in contrast showed significantly reduced IL-1β levels upon infection, indicating that NLRP3 inflammasome components (ASC) and targets (caspase-1) function upstream of GSDMD and have a potential dual role in cell death and release of pro-inflammatory cytokines." (PMID 34718331, 2021). "At 24 h post-infection with J2315, WT BMDMs showed pronounced cleavage of both Caspase-1 and Gasdermin-D, which was either absent or reduced in Casp1/11-/- and Ifnar1-/- BMDM, respectively." (PMID 33684179, 2021). "Collectively, these results suggest that induction of cell death by the ΔpknF mutant was independent of GSDMD and ΔpknF mutant infection results in both GSDMD-dependent and -independent secretion of IL-1β." (PMID 34324582, 2021). "GSDMD mRNA was stimulated, and GSDMD-C (cleaved GADMD C domain) increased in SFTSV infection THP-1 cells compared with mock infection, which indicated that SFTSV could induce pyroptosis." (PMID 33708197, 2021).
infection (continued). "Similar to the phenotype observed in Casp8/Ripk3/Casp1/11−/− mice, B. thailandensisvgrG5ΔCTD infection was also attenuated in mice lacking caspase-1/11 or GSDMD." (PMID 34154417, 2021). "We found the expressions of mRNA expression of caspase-1, GSDMD, caspase-3, MLKL, RIPK3, NLRP3, IL-1β and IL-18 and of proteins cleaved caspase-1, GSDMD, cleaved caspase-3 and pMIKL in the macrophages of the three infection groups to be upregulated (P<0.05)." (PMID 34513732, 2021). "VSV or EMCV infection induced the release of many proteins into the cell culture medium, and the release was unaffected by the absence of GSDMD." (PMID 31024004, 2019). "While MNV-induced diarrheic responses were not affected, Stat1-/- mice additionally lacking either Nlrp3 or GSDMD displayed lower levels of the fecal inflammatory marker Lipocalin-2 as well as delayed lethality after gastrointestinal MNV infection." (PMID 31017981, 2019). "We tested by western blot if GSDMD is activated in response to L. pneumophila and found that GSDMD is cleaved in response to wild type L. pneumophila but not flaA mutants after 6 hs of infection." (PMID 31251782, 2019). "Recent studies have demonstrated that infection with G. parasuis serotype 5 triggers an inflammatory response by activating the NLRP3 inflammasome and induces pyroptosis through the cleavage of gasdermin D (GSDMD) and the activation of Caspase-1, thereby amplifying the inflammatory cascade." (PMID 40665414, 2025). "For example, infections with pseudorabies virus, severe acute respiratory syndrome coronavirus 2 (SARS-CoV-2), respiratory syncytial virus, influenza A virus (IAV), and Streptococcus induce GSDMD-mediated pyroptosis to elevate the release of proinflammatory cytokines (22, 28, –, 34)." (PMID 40503916, 2025). "Interestingly, in severe influenza A virus (IAV) infection, GSDMD promotes disease in mice, but infection-induced release of IL-1β is also independent of GSDMD." (PMID 40016339, 2025). "Notably, the intensity of GSDME, GSDMD, caspase-3, and caspase-1 cleavage was strikingly more pronounced over the time course of Brazil/78 infection, correlating with significantly greater IL-1β and LDH release at 18 and 24 h post-infection." (PMID 40481027, 2025). "As infection progressed, we could observe a slight decrease in band intensity for FL GSDMD and GSDME in whole cell lysates (WCL), but not a clear appearance of GSDMD and GSDME cleaved products." (PMID 38932190, 2024). "Upon activation by NLRP3 inflammasome, Caspase-1 can cleave Gasdermin D (GSDMD) to form GSDMD-N, which bounds to phosphatidylinositol phosphates and phosphatidylserine presented in the inner leaflet of cell membrane, and induces the pyroptosis during the intracellular infection by S. aureus." (PMID 38515339, 2024). "Analysis of C-terminal GSDMD in infected versus non-infected macrophages indicates that the majority of the cells with cleaved C-terminal GSDMD at 2 h are infected as opposed to 24 h infection." (PMID 36828815, 2023). "Therefore, we predict that F1 and A47 are largely non-functional during MVA infection because we observed inflammasome assembly, GSDMD processing, IL-1β secretion and pyroptotic cell death in MVA-infected macrophages." (PMID 38065956, 2023). "At the same late time of 24 h post-infection, the Ripk3−/− BMDMs showed almost WT levels of activation of many PANoptosis molecules, consistent with the cell death phenotype we observed; however, Ripk3−/− BMDMs continued to show significantly reduced CASP1 and GSDMD activation at the 24 h timepoint." (PMID 38005819, 2023). "GSDMD is not always protective against infections; instead, it may worsen infections and pathological inflammation by potentially leading to a cytokine storm." (PMID 38002346, 2023). "Absence of SARM1 resulted in enhanced levels of processed GSDMD upon infection." (PMID 35947948, 2022).